GRM5 (glutamate metabotropic receptor 5)
Description:
G protein-coupled receptor for glutamate. Ligand binding causes a conformation change that triggers signaling via guanine nucleotide-binding proteins (G proteins) and modulates the activity of down-stream effectors. Signaling activates a phosphatidylinositol-calcium second messenger system and generates a calcium-activated chloride current. Plays an important role in the regulation of synaptic plasticity and the modulation of the neural network activity.
Synonyms: mGluR5; GPRC1E; mGlu5; PPP1R86
Tractability: Small molecule: a drug acting on it is in phase 2 or 3 trials; a structure with a bound ligand is known; a high-quality ligand is known; it has a high-quality binding pocket; it belongs to a druggable protein family. Antibody: UniProt places it where antibodies can reach, with high confidence; its Gene Ontology location is reachable by antibodies, with high confidence; UniProt predicts a signal peptide or a membrane-spanning region. PROTAC: ubiquitination databases record sites on it; its protein half-life has been measured; a small molecule that binds it is known.
Target class: Family C G protein-coupled receptor; Metabotropic glutamate receptor; Small molecule receptor (family C GPCR); Membrane receptor; Neurotransmitter receptor (family C GPCR)
Chemical probes: HTL14242 (high quality), ML254, ML332, ML353, PF470 (high quality), VU 0409106 (high quality), VU0424465
Gene: Protein-coding gene on chromosome 11 (88,504,576 to 89,065,982, reverse strand). Ensembl gene ENSG00000168959.
Subcellular location: Cell membrane
Pathways (Reactome):
Signal Transduction: Class C/3 (Metabotropic glutamate/pheromone receptors); G alpha (q) signalling events
Neuronal System: Neurexins and neuroligins
Gene Ontology:
Molecular function: G protein-coupled receptor activity; glutamate receptor activity; identical protein binding; protein binding; protein tyrosine kinase activator activity; adenylate cyclase inhibiting G protein-coupled glutamate receptor activity; G protein-coupled receptor activity involved in regulation of postsynaptic membrane potential; protein tyrosine kinase binding; A2A adenosine receptor binding
Biological process: cellular response to amyloid-beta; cognition; G protein-coupled glutamate receptor signaling pathway; phospholipase C-activating G protein-coupled glutamate receptor signaling pathway; positive regulation of calcium-mediated signaling; chemical synaptic transmission; learning or memory; regulation of synaptic transmission, glutamatergic; synapse organization; adenylate cyclase-inhibiting G protein-coupled glutamate receptor signaling pathway; associative learning; conditioned place preference; desensitization of G protein-coupled receptor signaling pathway; G protein-coupled receptor signaling pathway; negative regulation of dendritic spine morphogenesis; negative regulation of excitatory postsynaptic potential; operant conditioning; positive regulation of cellular response to hypoxia; positive regulation of cytosolic calcium ion concentration; positive regulation of dopamine secretion; positive regulation of intracellular signal transduction; positive regulation of long-term neuronal synaptic plasticity; positive regulation of MAPK cascade; positive regulation of neural precursor cell proliferation; positive regulation of sensory perception of pain; and 11 more
Cellular component: dendrite; plasma membrane; postsynaptic density membrane; astrocyte projection; dendritic shaft; dendritic spine; glutamatergic synapse; membrane; neuron projection; neuron spine; neuronal cell body; nuclear inner membrane; postsynaptic membrane
Genetic constraint (gnomAD): Loss-of-function variants: 15 observed, 53.68 expected, observed/expected ratio (o/e) 0.28, 90% interval 0.19 to 0.43. The upper end of that interval is the gene's LOEUF score, 0.43, which puts it in group 1 of 6, group 1 being the genes least tolerant of losing a copy. Missense variants: 970 observed, 1,296.5 expected, observed/expected ratio (o/e) 0.75, 90% interval 0.71 to 0.79. Synonymous variants: 591 observed, 523.73 expected, observed/expected ratio (o/e) 1.13, 90% interval 1.05 to 1.21.
Homologues: Orthologues: chimpanzee GRM5 (99% identical), macaque GRM5 (99% identical), pig GRM5 (97% identical), dog GRM5 (97% identical), mouse Grm5 (95% identical), rat Grm5 (95% identical), tropical clawed frog grm5 (81% identical), rabbit GRM5 (77% identical), zebrafish grm5b (72% identical), zebrafish grm5a (70% identical), guinea pig GRM5 (66% identical), Caenorhabditis elegans mgl-2 (32% identical). Paralogues in human: GRM1 (60% identical), GRM2 (32% identical), GRM3 (32% identical), GRM8 (31% identical), GRM4 (31% identical), GRM7 (31% identical), GRM6 (29% identical).
Diseases named in the same sentence as GRM5 in open-access papers:
GRM5 is named in the same sentence as 203 diseases in open-access papers, as found by Europe PMC text mining. Sharing a sentence is not in itself a finding about the gene and the disease. The quoted sentences say what the papers report.
Anxiety (85 papers, 2009 to 2026). Intense feelings of nervousness, tension, or panic often arise in response to interpersonal stresses. "Male animals born from mothers fed the palatable diet, and who continued with this diet after weaning, exhibited anxiety associated with an overexpression of the mRNA of Grin1, Gria1 and Grm5 glutamate receptors in the prefrontal cortex." (PMID 32575416, 2020). "In the hippocampus and hypothalamus, GEG increased expression of GRM5, a receptor essential for cortico-limbic circuit integrity and pain modulation, with augmented mGluR5 translating to increased glutamate signaling, whose downregulation has been linked to stress vulnerability and anxiety." (PMID 41515464, 2026). "Examining the mRNA SLC1A2, SLC1A3, GRM5, GRIN2B, GRIN2C, GRIA1, CHRNA7, 5-HT2A, and 5-HT3A offers insight into the neurotransmission systems implicated in NP-related anxiety." (PMID 41515464, 2026). "Loss of Grm5 induces ASD-like phenotypes, including impaired social interaction, repetitive behaviors, and anxiety-like behaviors." (PMID 41150532, 2025). "Previous studies have shown that germline Grm5 deletion or systemic application of mGlu5 antagonists change the expression of several emotional behaviors including social interaction, anxiety-like behavior and fear responses." (PMID 38575807, 2024). "GRM1 and GRM5 are type I metabotropic glutamate receptors involved in various mental illnesses, including depression, anxiety, and cognitive impairment by regulating the function of neurotransmitters such as glutamate, dopamine, and norepinephrine." (PMID 36210820, 2022). "In the present study, the significant downregulation of Grm5 (Log2FC = −2.9638, p = 0.0006) suggests that Grm5 may play a critical role in autism-like anxiety behaviors by disrupting cerebellar glutamate transmission." (PMID 41150532, 2025). "However, given the increased anxiety-like behavior showed by Grm5-/- mice, the sociability expressed by these animals in the three-chambered social task might have been underestimated." (PMID 30873001, 2019). "Considering that variation in the human mGluR5 gene (GRM5) has been linked to alcohol dependence, the present findings may provide additional insight to the relationship between GRM5 variation and its influence on traits such as anxiety and sensation seeking." (PMID 21152045, 2010). "When tested for measures of anxiety-like behavior, SSTCre-Grm5−/− male, but not female, mice spent more time in the open arms of the elevated plus maze test as compared to control animals." (PMID 38575807, 2024). "Unlike OSS, haploinsufficiency of the grm5 gene did not significantly affect anxiety-like behavior." (PMID 21152045, 2010).
fragile X syndrome (80 papers, 2009 to 2025). A genetic syndrome caused by mutations in the FMR1 gene which is responsible for the expression of the fragile X mental retardation 1 protein. "In a recent study, mGluR5 has been shown to participate in the pathogenesis of fragile X syndrome (FXS) while genetic downregulation of Grm5 was able to compensate for some of the symptoms in a mouse model of FXS." (PMID 24355397, 2013). "For example, Bakker and Oostra studied the Drosophila model for fragile-X syndrome and found individuals with arrhythmic and erratic patterns of locomotor activities and abnormal circadian behaviour, which were regulated by the metabotropic glutamate receptor 5 protein (GRM5)." (PMID 36104821, 2022).
schizophrenia (78 papers, 2011 to 2026). A major psychotic disorder characterized by abnormalities in the perception or expression of reality. "The gene encoding the mGluR5 (GRM5) is a promising target for the treatment of various symptoms of schizophrenia." (PMID 39858450, 2025). "In NeuN+ nuclei, several genes encoding metabotropic glutamate receptors (GRM3, GRM5) that are directly associated with schizophrenia risk were found differentially expressed in both studies." (PMID 38648100, 2024). "Although GRM5 (coding for metabotropic glutamate receptor 5, mGluR5) is a promising target for treating cognitive deficits in schizophrenia and AD, its association with cognitive and brain phenotypes within this disorder has received little attention." (PMID 36561136, 2022). "Of seven overlapping genes, Grm5, encoding mGluR5, was the most highly ranked z score of seven DEPs (z score = 12.8 and P = 0.008) and also displayed schizophrenia-associated up-regulation in the PsychENCODE brain RNA-seq dataset (log2FC = 0.043 and P = 0.02)." (PMID 35984881, 2022). "It has been showed that that genetic mutations in GRM5 are associated with cognitive impairments and right hippocampal volume reduction in schizophrenia." (PMID 32512843, 2020). "Supporting this hypothesis, the mGluR5 GRM5 gene has recently been suggested as one of the top candidate genes for schizophrenia vulnerability, with exome sequencing of multiplex pedigrees reporting disruption to the mGluR5/Tamalin association." (PMID 24472577, 2014). "In more detail, we found one Rab32 always coupled with the melanoma oncogene Grm1, while one Rab38 is always close to Grm5, a gene playing a fundamental role in many human disorders such as schizophrenia and autism." (PMID 26818140, 2016). "We also showed a primate gained TAD boundary containing the gene GRM5, a promising target for the treatment of cognitive deficits in schizophrenia, which may be involved in the regulation of neural network activity and synaptic plasticity." (PMID 35524220, 2022). "GRM5 (coding for metabotropic glutamate receptor 5, mGluR5) is a promising target for the treatment of cognitive deficits in schizophrenia, which may be related to the reduction of hippocampal volume." (PMID 32392183, 2020). "The molecules that mostly contributed to discriminate schizophrenia from control were: VGluT2, EAAT2, GAD67, d-Asp/total Asp, d-Ser, PSD-95, GRIA1 and GRM5 whereas the ones that barely contributed to the discrimination were: l-Gln/l-Glu ratio, d-Ser/total Ser, EAAT1, GRIN2A and Gly." (PMID 35217646, 2022).
depression (73 papers, 2009 to 2026). "GRM5 (Glutamate Metabotropic Receptor 5) was previously associated with smoking behavior and incorporated in smoking cessation studies and has also previously been associated with depression." (PMID 38790194, 2024). "In addition to GRM5, ELAVL4, implicated in depression and in epigenome-wide association studies of suicide, was significant in females, but not males." (PMID 36750733, 2023). "We next sought to determine which formulation was superior in treating mild-to-moderate COVID-19 with symptoms of depression or inflammation via targeting specific targets (GRM1, GRM5, mTOR and PLA2G4A)." (PMID 36210820, 2022). "The genes that are potentially of interest for the study of depression include the Neural Growth Regulator 1 (NEGR1), the glutamate metabotropic receptor 5 (GRM5), the glutamate ionotropic receptor kainate type subunit 3 (GRIK3) and the transmembrane protein 106B (TMEM106B) protein coding genes." (PMID 29662059, 2018). "Among GWAS genes that interacted the most with depression portrait genes were the histone acetyltransferase, EP300, the Rho GTPase, RHOA, the heat shock protein HSPA1A, the dopamine receptor, DRD2, the glutamate receptor, GRM5, the huntington gene, HTT, and the estrogen receptor, ESR2." (PMID 33589676, 2021).
Alzheimer disease (49 papers, 2011 to 2025). A progressive, neurodegenerative disease characterized by loss of function and death of nerve cells in several areas of the brain leading to loss of cognitive function such as memory and language.
epilepsy (37 papers, 2011 to 2025). A brain disorder characterized by episodes of abnormally increased neuronal discharge resulting in transient episodes of sensory or motor neurological dysfunction, or psychic dysfunction. "This gene is interesting because Grm5−/− mice have increased susceptibility to pharmacologically induced seizures and the human protein product is highly connected to the epilepsy training genes." (PMID 24086149, 2013). "The detected increase in Grm5 mRNA production and a decrease in group III members’ expression were likely to contribute to the development of epilepsy in the latent phase of the model." (PMID 35269897, 2022).
encephalitis (32 papers, 2017 to 2026). An acute inflammatory process affecting the brain parenchyma. "Inspired by a case of pediatric Ophelia syndrome with severe mGluR5 antibody encephalitis, we provided experimental evidence of heterogeneous mGluR5/GRM5 expression in different HL cell lines and in tumor tissue of the index patient." (PMID 39001514, 2024).
autism spectrum disorder (17 papers, 2013 to 2025). A spectrum of developmental disorders that includes autism, and Asperger syndrome. "Grm5 was targeted because of the over-activation of mGluR5-dependent signaling present in FXS and other autism spectrum disorders." (PMID 30669625, 2019).
Huntington disease (16 papers, 2013 to 2025). Huntington disease (HD) is a rare neurodegenerative disorder of the central nervous system characterized by unwanted choreatic movements, behavioral and psychiatric disturbances and dementia. "TBP, GRM5, and GRIA1 were co-enriched in Huntington’s disease pathway." (PMID 36561136, 2022).
melanoma (14 papers, 2016 to 2025). A malignant, usually aggressive tumor composed of atypical, neoplastic melanocytes. "Mutations in GRM5 influenced Ca2+ oscillations in transgenic mice that showed tumour/melanoma phenotype in addition to dramatic increase in phosphorylation of ERK in these tumour samples." (PMID 26730743, 2016). "SNPs in another locus on chromosome 11, near genes GRM5 and TYR, have been associated with skin cancer, melanoma, skin sensitivity to sun, insomnia, tan response, sunburns and hearing loss." (PMID 39975919, 2025). "Transgenic mice overexpressing Grm5 (Tyrp1-Grm5) present with multiple melanoma located on the tail, with 100% penetrance and metastases, demonstrating that Grm5 drives melanoma initiation and progression." (PMID 35158973, 2022). "Glutamate release promotes the growth and metastasis of malignant gliomas and melanoma through GRM5 and the downstream PI3k/Akt pathway." (PMID 31492116, 2019). "Examples of metabotropic glutamate receptors being implicated in development of cancers are the involvement of GRM1 and GRM5 in the induction of melanoma in transgenic mice." (PMID 26730743, 2016). "In contrast to Grm1, Grm5 is normally expressed in both normal melanocytes and melanoma tumors." (PMID 35158973, 2022). "Our group has shown earlier that the complete knockout of GRM5 did not alter melanoma pathogenesis driven by the ectopic expression of mGluR1-mediated melanomagenesis." (PMID 36139432, 2022). "The antagonist of GRM5 could significantly induce a reduction in cell proliferation of laryngeal cancer RK33 and RK45 cells, and GRM5 overexpression promoted melanoma development in transgenic mice, indicating that GRM5 functions as an oncogene in laryngeal cancer and melanoma." (PMID 34950209, 2021). "However, GRM1 agonist, L-quisqualate, was the only compound tested that lowered xCT expression in melanoma cells (data not shown) suggesting that other possible effectors of xCT may be present other than GRM1 such as GRM5 or AMPA receptors." (PMID 30425240, 2018).
Obesity (8 papers, 2014 to 2023). Accumulation of substantial excess body fat. "We also found a 1.59 kb copy number deletion (dbVar ID: nssv15803200, 11:49759283–49,760,872) within intron 2 of GRM5P1(GRM5 pseudogene 1) associated with early obesity." (PMID 38110883, 2023).
Stroke (8 papers, 2013 to 2026). Sudden impairment of blood flow to a part of the brain due to occlusion or rupture of an artery to the brain. "Therefore, the downregulation of Grm5 in a CIR-induced stroke indicated a self-protective mechanism of the brain, albeit with less neurogenesis, which might result in a poorer motor function." (PMID 26492191, 2015).
alcohol dependence (7 papers, 2010 to 2021). Physical and psychological dependence on alcohol. "The Grm5 gene has been linked to alcohol dependence in both humans and mice." (PMID 29674951, 2018).
glioma (7 papers, 2009 to 2024). A benign or malignant brain and spinal cord tumor that arises from glial cells (astrocytes, oligodendrocytes, ependymal cells). "Functional analysis of the DEGs showed that GALR1 and GRM5 of neuroactive ligand-receptor interactions signaling pathways may be relaed to malignant progression of gliomas." (PMID 31537867, 2019). "The different expression levels of GRM3 and GRM5 in “NT-type” and “NOS-type” was confirmed; however, the difference between low-grade gliomas and GMB was variable and dataset-dependent." (PMID 38509672, 2024).
Intellectual disability (7 papers, 2012 to 2024). "Amongst the metabotropic receptors, Glu receptor 5 (GRM5), triggering a variety of signaling pathways in the neurons and glial cells, was reported to have an association with intellectual disability and Autism42." (PMID 37964012, 2023).
liver fibrosis (7 papers, 2021 to 2026). "Notably, gene hubs like Drd1, Gria1‐4, Grin1, Grin2b, Grm5, and GABAα receptor genes were also highly connected, mirroring gene expression patterns observed in liver fibrosis, cirrhosis, and hepatocellular carcinoma (HCC)." (PMID 41508419, 2026).
oral squamous cell carcinoma (7 papers, 2010 to 2023). "GRM5 was highly expressed in oral squamous cell carcinoma and contributed to tumor cell migration and invasion." (PMID 35267472, 2022). "For instance, the high expression of GRM5, a member of group I, was reported to be related to the improved overall survival in human oral squamous cell carcinomas." (PMID 34950209, 2021). "In addition, GRM5 was found to play a role in tumour cell migration and invasion in oral squamous cell carcinoma and found to be overexpressed in lung cancer cells." (PMID 26730743, 2016).
nicotine addiction (6 papers, 2018 to 2025). "Interestingly, we found that Grm5 involved in reward- and nicotine dependence (ND)-related behaviors was widely expressed in all types of neurons examined in this study." (PMID 41395251, 2025).
hepatocellular carcinoma (5 papers, 2022 to 2026). A malignant tumor that arises from hepatocytes. "Inhibiting GRM5 expression could suppress oncogenic actions by blocking downstream signaling factors in hepatocellular carcinoma." (PMID 35267472, 2022).